ALK (ALK receptor tyrosine kinase)
Diseases named in the same sentence as ALK in open-access papers (continued):
Sharing a sentence is not in itself a finding about the gene and the disease.
tumor (continued). "Many evidences support that ALK is spontaneously recognized as a tumor antigen in human patients." (PMID 29495603, 2018). "Fluorescent in situ hybridization (FISH) for MET-amplification, immunohistochemistry (IHC) for MET- and ALK-expression, and Next Generation Sequencing (NGS) for concomitant driver mutations were performed on EGFR-mutated tumor samples from erlotinib-treated patients." (PMID 29899852, 2018). "Furthermore, increased plasma levels of miR-660-5p after treatment with crizotinib were correlated with good tumor response in patients who had ALK-positive NSCLC." (PMID 28514730, 2017). "The high level of ALK fusion protein expression in cancer cells and its direct role in tumorigenesis, in line with the fact that normal ALK is expressed at low levels in the immune privileged nervous system, makes it an ideal tumor-specific target for immunotherapy in ALK fusion-positive NSCLC." (PMID 29189709, 2017). "Most importantly, as therapeutically-induced autophagy can drive tumor cells’ fate towards survival, or oppositely, towards death, the identification of the actors and regulators of this switch should provide more effective ALK-cancers therapies." (PMID 29186933, 2017). "Thus, constitutive ALK activation confers multiple advantages to tumor cells that are essential for successful malignant progression." (PMID 28837676, 2017). "Therefore, converting the TME in ALK+ NSCLC to such extent that an effective immune response against the tumor will become possible remains an important challenge." (PMID 29189709, 2017). "In order to see whether ALK was also expressed at protein level, we performed immunohistochemistry on tumor and normal skin tissue sections using two different antibodies." (PMID 28359267, 2017). "Additionally, the multiplex RT-PCR can sensitively detect not only certain ALK fusion gene variant even in formalin-fixed paraffin-embedded (FFPE) tissue sections, but also the abundance of EML4-ALK positive cells in NSCLC tumor tissues." (PMID 29088875, 2017). "The ALK status can also be evaluated using circulating tumor cells (CTCs)." (PMID 29125548, 2017). "Thus, accumulating data shows that the DNA methylation and silencing of tumor suppressor genes plays a key role in NPM/ALK-induced malignant transformation." (PMID 28771164, 2017). "ALK copy number was also assessed in both plasma-derived cfDNA and tumor gDNA using ddPCR." (PMID 29156716, 2017). "The lack of mutations in KRAS, EGFR and ALK genes in CRC cultured tumor specimens suggested that the cells growing in CRC conditions are mostly non-malignant." (PMID 28052041, 2017). "Therefore, targeted NGS is sensitive enough to identify ALK fusion across a large range of ALK expression level, which demonstrates high tumor heterogeneity." (PMID 28882180, 2017). "All ALK positive tumor samples by IHC also showed high RNA expression." (PMID 28359267, 2017). "Similarly, to identify miRNAs differentially expressed between ALK+ and ALK- NB tumors we first analyzed ALK mRNA expression in a set of tumor samples to determine subgroups of NBs expressing low or high levels of ALK." (PMID 28915608, 2017). "ALK expression was seen in all patients with high levels in 22/26 tumor samples." (PMID 28359267, 2017). "In animals with high tumor burden, the anti-tumor effect of an ALK vaccine is diminished." (PMID 29189709, 2017). "In agreement with this, our previously reported ALKR1275Q knock-in and MYCN transgenic compound mice revealed that the co-operation of ALK mutation and MYCN overexpression results in impaired normal extracellular matrix/basement membrane integrity and enhanced tumor growth and dissemination." (PMID 29296183, 2017).
tumor (continued). "The mean disease-free survival was 39.0 months in ALK IHC-negative patients versus 26.3 months in ALK IHC-positive patients (P = 0.001), and the tumor recurrence rate was significantly higher in the ALK IHC-positive group (59.5% vs 35.4%, respectively; P = 0.003)." (PMID 29156778, 2017). "After their death, tumor specimens were tested for ALK positivity and IMT diagnosis was done." (PMID 29310405, 2017). "By these immunohistochemical assays, we could not find a statistically significant difference between patients with high vs low ALK antibodies titers for the amount of T cell infiltrates or the expression of PD-L1 by the tumor cells." (PMID 29190913, 2017). "However, after two months, the oncologist asked for PD-L1 analysis and noted that ALK analysis was missing from both the right lower lobe tumour and its left lower lobe metastasis." (PMID 28347348, 2017). "Thus, the combination of an ALK vaccine and ALK inhibitors, as expected, increased the anti-tumor efficacy due to an increase of neoantigens and possible tumor microenvironment changes (e.g., more tumor-infiltrating lymphocytes)." (PMID 29189709, 2017). "Also, ALK inhibition has been shown to decrease the biological effects of MYCN amplified cells/tumor growth in xenograft models." (PMID 29018329, 2017). "Moreover, ceritinib and the other next-generation ALK inhibitors are more potent than crizotinib and can overcome tumor cell resistance mechanisms." (PMID 28805682, 2017). "In addition, the ALK gene translocations were evaluated in a series of 53 primary tumours and their paired lymph node metastases using ALK D5F3 IHC staining." (PMID 28887531, 2017). "These targeted therapies have further developed as a result of advancements in tumour analysis for protein mutations that cause uncontrolled proliferation, such as those in epidermal growth factor receptor (EGFR) and anaplastic lymphoma kinase (ALK)." (PMID 28955400, 2017). "We agree it is difficult to draw certain conclusions given the evidence of today, though in our opinion, different driver mutations (such as EGFR or KRAS mutations or ALK or ROS1 rearrangements, like in our cases 4 and 6) probably quite strongly support synchronous/metachronous tumours." (PMID 28347348, 2017). "In addition, ALK mRNA and protein expression were detected in tumor microvasculatures composed of endothelial cells and mural cells." (PMID 28837676, 2017). "Furthermore, in transgenic mice expressing EML4-ALK under a lung-specific promoter, treatment with an ALK vaccine after lung tumors had already formed significantly reduced tumor growth and extended survival in vaccinated mice compared to control mice." (PMID 29190913, 2017). "Based on these findings, it can be see that ALK and EGFR after requiring functional mutation could drive the growth of tumor cells via PI3K-AKT pathway." (PMID 29152079, 2017). "ALK was considered positive when at least 10% of the tumor cells stained with an intensity ≥2." (PMID 28638113, 2017). "Induction of tumor PD-L1 expression likely occurs in response to inflammation induced by host antitumor immune responses and through tumor-specific mutations, such as loss of the tumor-suppressor PTEN or enhanced ALK gene signaling." (PMID 29207684, 2017). "Molecular testing for ALK translocation may be performed in either primary tumour or lymph node metastasis samples from the same patient." (PMID 28887531, 2017). "Multivariate analysis showed that ALK IHC-positivity was an adverse prognostic factor for disease-free survival (HR, 1.80; 95% CI 1.18-2.77; P = 0.007), tumor-specific survival (HR, 2.59; 95% CI 1.35-4.97; P = 0.004), and overall survival (HR, 1.92; 95% CI 1.07-3.44; P = 0.030)." (PMID 29156778, 2017). "Although selective ALK inhibitors represent an emerging strategy to treat ALK+ neoplasms including NPM‐ALK+ T‐cell lymphoma, several resistance mechanisms to these inhibitors have been already identified and characterized, which represents an important limitation." (PMID 28557340, 2017).
tumor (continued). "A total of 57 ALK+ ALCL with at least 40% tumour cell content were analysed." (PMID 26753883, 2016). "This suggests that the ALK mutation was gained after duplication of the EML4-ALK fusion or that the mutation is present only in a proportion of the tumor cells, while being wild type in the other tumor cells." (PMID 27045755, 2016). "Knockdown of either ALK or CRKL in this primary tumor line also inhibited cell viability." (PMID 27078848, 2016). "Besides ALK, tumor cells stained variably for desmin (4/5), alpha smooth muscle actin (2/5), muscle-specific actin (1/2) and pan-cytokeratin (1/4)." (PMID 27460384, 2016). "Tumor histology was reviewed in 11 surgically resected cases of the 26 ALK-positive cases." (PMID 27142166, 2016). "Other currently unknown ALK-independent resistance mechanisms might have been induced in this tumor sample." (PMID 27045755, 2016). "It has been shown that in the same ALK resistant tumor, multiple mechanisms of resistances may occur." (PMID 26951079, 2016). "Such knowledge may provide clinically valuable pharmacokinetic details that may be used to stratify tumors for ALK-targeted therapy or to predict the response of an individual tumor to such treatment." (PMID 27732954, 2016). "Although not all tissue variants could be confirmed in the matched serum, up to 57% of the tumor variants were reflected in matched cfDNA with mutations in PIK3CA, ALK, and PTEN as well as variants at COSMIC annotated sites in all six patients analyzed." (PMID 27529345, 2016). "However, TCR expression is required for thymic egress and development of peripheral tumours which, for the first time, histologically resemble human ALK+ ALCL." (PMID 26753883, 2016). "The tumor of this patient exhibited an extensive papillary and micropapillary pattern with partly retained alveolar wall architecture, distinguishing it histologically from the usual pattern of ALK-rearranged tumors." (PMID 27756333, 2016). "We did not observe any evidence for genetic heterogeneity in the surgical specimen, i.e., the ALK fusion event was present in all tumor cells which is consistent with the concept of mutual exclusivity with other main drivers, e.g., mutant EGFR, and the notion that ALK fusion are truncal mutations." (PMID 27863497, 2016). "Recapitulation of ALK rearrangement patterns in the tumor on CTCs, suggested that CTCs might be used to complement tissue-based ALK testing in NSCLC to guide ALK-targeted therapy when suitable tissue biopsy samples are unavailable for testing." (PMID 26993609, 2016). "Besides ALK, tumor cells also showed variable expression of desmin (4/5), smooth muscle actin (2/5), muscle-specific actin (1/2) and AE1/AE3 (1/5)." (PMID 27460384, 2016). "These ELM4-ALK positive tumours, like those with mutations in EGFR, either show a lack of response to ALK-specific TKIs such as crizotinib (Xalkori) or relapse with drug resistant disease." (PMID 26791049, 2016). "The ALK translocation with different genes defined the second biggest group of so called oncogene-addicted tumours after EGFR mutated ones, but this evidence happened with the discovery of activity in vitro cell lines and in vivo mouse models of ALK inhibitors." (PMID 27433281, 2016). "In addition, we have successfully established a tumor cell line from an ALK-rearranged NSCLC patient (designated as MP038) as a part of our molecular profiling clinical trial program (Trial ID: NCI-11-C-0096 and NCT01306045)." (PMID 27078848, 2016). "This suggests that the ALK-rearranged CTC population might be a consequence of clonal selection from a specific subpopulation of primary tumor cells, and that outgrowth of this subpopulation can be an indication for therapy resistance." (PMID 26980749, 2016). "Furthermore, studies showed that positive ALK protein expression correlates with tumor response to ALK inhibitors." (PMID 27769042, 2016).
tumor (continued). "From a biomolecular point of view, near one half of tumours ALK positive treated with crizotinib develop a secondary resistance mutation as gatekeeper mutation like L1196M, which gives a further tumoural ‘gain of function’ under the selective pressure of crizotinib exposure." (PMID 27433281, 2016). "(B) Western blot on total lysate and ALK-immunoprecipitated fraction of #187 ERMS tumor." (PMID 26987019, 2016). "Thereby, it is important to keep in mind that even for the known variants of ALK fusion genes the biological function is not known for all variants and that no information is available on the homogeneity of ALK fusion variants within a single tumor." (PMID 26784235, 2016). "It is a highly selective ALK inhibitor with activity also in RET translocated tumours." (PMID 27433281, 2016). "Sixth, although ALK-positive patients were more likely to have a small tumor compared to EGFR-positive patients, this may be because of indolent nature of EGFR-positive tumors." (PMID 27518729, 2016). "Indeed, while visualization of ALK protein by Western blot in the primary tumor extract required enrichment by immunoprecipitation, L cells expressed unusually high levels of ALK at baseline." (PMID 26987019, 2016). "In addition, because of insufficient samples, we didn’t detect ALK fusion gene in adnexal tumor tissue by fluorescence in situ hybridization (FISH) assay again." (PMID 27472693, 2016). "Previous studies demonstrated that EGFR and ALK genes could induce PD-L1 expression to facilitate evasion of the host anti-tumour immune response, suggesting an active role for these genes in remodelling the immune microenvironment." (PMID 27342566, 2016). "Studying the pattern of resistance to crizotinib or ceritinib, it clearly emerges that every ALK-positive tumours could virtually develop different secondary resistance mutations, which may be blocked by a second or third generation ALK-TKI." (PMID 27433281, 2016). "The average number of ALK FISH positive tumor cells was 24.6% (range 20.7-30.5%)." (PMID 27769042, 2016). "Because a large tumour sample often included both NLRR1-rich/ALK-poor and NLRR1-poor/ALK-rich cancer cells (samples #3, #4, and #5), the opposite expression pattern of NLRR1 and ALK might be masked in the homogenised mRNA samples." (PMID 27604320, 2016). "Recently the early results of a phase I/II study with lorlatinib in heavily pretreated chemo and ALK/ROS1 TKIs showed an interesting response rate of 44% with a safe profile demonstrating the activity of this compound even in tumours considered highly refractory to ALK inhibition." (PMID 27433281, 2016). "However, RT-PCR demonstrated ALK rearrangement in one case that provided insufficient tumor cells for FISH and in two cases that showed uninterpretable signals by FISH." (PMID 27142166, 2016). "ALK FISH signal patterns observed on tumor biopsies were recapitulated in CTCs in all cases." (PMID 26993609, 2016). "Recently, a very sensitive RT-PCR-based method was devised to detect the overexpression of 3′ regions of fusion transcripts involving tumour genes constitutionally repressed or expressed at very low levels; this approach has been successfully applied to ALK gene fusions in lung cancer." (PMID 27535289, 2016). "Consequently, the FDA approved method for the detection of ALK rearrangements is FISH while the EMA allows use of any method in Europe that correctly identifies patients whose tumor harbors ALK fusions." (PMID 27863497, 2016). "Another crucial cascade involved in ALK signalling is the Ras / mitogen-activated ERK kinase (MEK) / extracellular signal-regulated kinase (ERK) pathway and its associated effectors that enhance tumour growth in many cancer models." (PMID 27669408, 2016). "In addition, siRNA-mediated ALK silencing markedly inhibited tumor cell invasion (72% of reduction compared to siR-CTR)." (PMID 27385213, 2016).
tumor (continued). "In this study we sought to investigate whether autophagy activation acts as a tumor survival mechanism to overcome ALK oncogene inactivation in ALCL cell lines and whether disabling autophagy may represent a clinical benefit for ALCL patients." (PMID 26338968, 2015). "However, the final diagnosis was corrected to an IMT due to ALK positivity and epithelial growth in the tumour cells, resulting in a good patient prognosis." (PMID 25910080, 2015). "PD-1 positive tumor infiltrating lymphocytes and PD-L1 expressing tumor cells were seen in 18 of 42 cases (43%) of which 8 cases lacked other biologic targets including EGFR mutations, HER2, cMET, ALK, or ROS1 rearrangements." (PMID 25941796, 2015). "Therefore, we synthesized several peptides whose sequence reproduced the entire ADD domain (36 aa) of ALK or part of it (12 aa) to assay their effects on various tumor cell lines." (PMID 25950466, 2015). "However surgical resectability with complete resection, tumour size and ALK expression are variables that have been known to alter prognosis and disease evolution." (PMID 25648655, 2015). "In these cases ALK expression is often of uncertain pathogenic significance and tumour cells do not exhibit the same dependency on receptor signalling." (PMID 26147305, 2015). "However, our patient’s tumor was a typical epithelial carcinoma, and ALK protein expression and ALK alterations of the rhabdomyosarcomatous component were both negative." (PMID 26358638, 2015). "In this context, we have recently generated targeted nanoliposomal formulations carrying ALK-directed siRNAs (TL[ALK-siRNA]), which are highly specific for the gene target and efficiently delivered to NB cells thanks to a selective tumor targeting provided by the carrier." (PMID 26299615, 2015). "ALK is a RTK that can be implicated as truncated fusion protein and full-length kinase in a number of solid and haematologic malignancies, and in most cases its inhibition leads to a marked decrease of tumour cells growth and survival." (PMID 26147305, 2015). "Furthermore, a preclinical study showed that ALK-amplified tumor cells isolated from IBC patients were highly sensitive to the anti-proliferative effect of crizotinib, but resistant to paclitaxel." (PMID 25803816, 2015). "Four of five patients with ALK-positive CNS metastatic lesions experienced tumor regression." (PMID 25941796, 2015). "However, as the disease progressed, the ALK gene status of the tumour was investigated, and based upon a positive result, the patient was treated with crizotinib and achieved a complete response." (PMID 25788996, 2015). "The ALK fusion gene exists in ~56% of IMTs and has been hypothesized to have significant effects in the process of tumor development." (PMID 25624905, 2015). "Collectively, our observations suggest that ALK may represent a potentially druggable target in RMS, although remains to be clarified whether RMS may be considered an ALK-positive tumour or an ALK-driven malignancy." (PMID 26147305, 2015). "Ceritinib, a second-generation ALK inhibitor, is effective in patients resistant to crizotinib as well as crizotinib-naive patients and is approved by the US Food and Drug Administration for patients who have tumor progression or are intolerant of crizotinib." (PMID 26219569, 2015). "In the case of the availability of tumor tissues, our results may be slightly skewed due to the small sample size tested for ALK rearrangements." (PMID 25789627, 2015). "In vivo and in vitro studies demonstrated that treatment with Hsp90 inhibitors such as 17-DMAG, ganetespib (STA-9090), or IPI-504 reduced protein levels of the ALK fusion protein, enhanced cell death, led to tumor regression, and prolonged survival of xenograft models." (PMID 26219569, 2015).